EFNB2 (ephrin B2)
Diseases named in the same sentence as EFNB2 in open-access papers (continued):
Sharing a sentence is not in itself a finding about the gene and the disease.
mesothelioma (1 paper, 2013). A usually malignant and aggressive neoplasm of the mesothelium which is often associated with exposure to asbestos. "We also found that the EphB4-Ephrin-B2 inhibitor sEphB4-HSA, alone or combined with the anti-VEGF antibody Bevacizumab was highly active in inhibiting mesothelioma growth in xenograft models." (PMID 23721559, 2013).
metastasis (1 paper, 2017). The spread or migration of cancer cells from one part of the body (where they first appeared) to another. "Clinical specimens from patients with OSCC had robust ephrin-B2-positive tumor cells and ephrin-B2 protein level was associated with clinical stage, lymph node metastasis, and poor survival outcomes." (PMID 29190834, 2017).
metastatic melanoma (1 paper, 2021). A melanoma that has spread from its primary site to another anatomic site. "Ephrin-B2–EphB4 communication induces tumor cell repulsion from the endothelium in metastatic melanoma, reducing spinal bone metastasis formation." (PMID 34360793, 2021).
microcephaly (1 paper, 2019). A congenital or acquired developmental disorder in which the circumference of the head is smaller than normal for the person's age and sex. "MIR17HG and ZIC2 loss was observed in a patient with digital anomalies, severe growth failure, microcephaly and corpus callosum agenesis while hemizygotic EFNB2 gene loss was identified in two patients, one of them with microphtalmia." (PMID 31976095, 2019).
Obesity (1 paper, 2021). Accumulation of substantial excess body fat. "Further studies are required to investigate the functional analysis of EFNB2 related to obesity." (PMID 33654129, 2021).
oral cavity cancer (1 paper, 2022). A primary or metastatic malignant neoplasm involving the oral cavity. "Blockade of EFNB2 in PDX tumor derived from a patient with recurrent oral cavity cancer inhibited tumor proliferation and increased animal survival." (PMID 36438491, 2022).
pilomatricoma (1 paper, 2019). "All tumours except pilomatricoma were positive for the expression of Ephrin B2." (PMID 31065284, 2019).
proliferative diabetic retinopathy (1 paper, 2019). Advanced retinopathy due to diabetes mellitus characterized by the formation of new vessels in the retina. "Increased expression of Ephrin-B2 has been reported in conditions associated with increased pathological angiogenesis such as proliferative diabetic retinopathy and tumor growth." (PMID 30620753, 2019).
skin cancer (1 paper, 2019). "We detected that CRABP1, Nestin, and Ephrin B2 are expressed in the intratumoural stroma as well as the tumour invasive front of skin tumours of appendages and BCCs." (PMID 31065284, 2019).
systemic vasculitis (1 paper, 2026). "Following entry via ephrin-B2 and ephrin-B3 receptors, NiV exhibits marked endothelial and neuronal tropism, leading to systemic vasculitis, disruption of the blood-brain barrier, and direct infection of the central nervous system." (PMID 42075770, 2026).
tongue squamous cell carcinoma (1 paper, 2017). A squamous cell carcinoma that arises from the tongue. "Furthermore, we found that metastasis to cervical lymph nodes from tongue squamous cell carcinoma was significantly suppressed by local injection of EFNB2 siRNA in vivo." (PMID 29190834, 2017).
vascular malformation (1 paper, 2019). A non-neoplastic disorder that is the result of defects of vascular morphogenesis. "Furthermore, whether the dysregulation of EphB1 and EfnB2 is only present in PWS or also in other types of congenital vascular malformations such as IHs is yet to be answered." (PMID 31067686, 2019).
tumor (141 papers, 2003 to 2025). "In PDAC, EFNB2 is overexpressed and associated with tumor progression, making it a potential treatment target." (PMID 39766812, 2024). "Consistent with this, high ephrin-B2 expression in breast tumours was associated with lower grade tumours and better patient prognosis, and its expression in vitro inhibited proliferation and migration." (PMID 36830852, 2023). "All these results consistently suggest that ITGA5, EFNB2 or p-S6 in tumor tissues have good sensitivity and specificity as diagnostic markers for LSCC." (PMID 36438491, 2022). "The targeting of EPHA2, EPHA10, EPHB4, ephrin-A2, ephrin-A4, as well as ephrin-B2 in BC cells or xenograft models is associated with apoptosis induction, tumor regression, anticancer immune response activation, and impaired cell motility." (PMID 36499598, 2022). "Ephrin-B2 expression was again reported higher in cancerous tissues, and its overexpression was linked to tumor TNM stage and high Ki67 expression." (PMID 34445116, 2021). "Ephrin-B2–EphB4 interactions have also been implicated in the interaction between tumor cells and osteoblasts in bone metastasis development." (PMID 34360793, 2021). "Another study linked EPHB4 and ephrin-B2 overexpression to higher tumor stage, LN metastasis, higher tumor size and poorer prognoses." (PMID 34445116, 2021). "First observations led to the assumption that a stronger expression of EFNB2 is associated with an increased vascularisation and tumour growth as observed in human colorectal cancer." (PMID 26044849, 2015). "In tumor angiogenesis, loss of Ephrin-B2 leads both to significantly reduced tumor vessel density and to tumor growth." (PMID 23721559, 2013). "Consistent with previous reports on ephrin-B2 induction in some epithelial tumors and tumor-associated vasculatures, EC8 specifically detected ephrin-B2 in tumors as well as the vasculature within and outside of the tumors." (PMID 22292016, 2012). "Paradoxically, overexpression of ephrin-B2 was associated with a marked decrease in tumour growth that was likely secondary to the development of an inefficient vascular network." (PMID 15083195, 2004). "Lastly, EFNB2 is highly expressed in certain tumor types and is linked to disease progression." (PMID 40141028, 2025). "In parallel, the EPHB4/ephrin-B2 targeting could suppress the pro-tumorigenic immune infiltrates, causing further tumor regression." (PMID 36769332, 2023). "Furthermore, targeting of EPHA10, EPHB4, ephrin-A2, and ephrin-A4, as well as ephrin-B2 in BC cells or xenograft models was associated with tumor regression, anticancer T-cell activation, and impaired cell motility." (PMID 36499598, 2022). "Interestingly, a role for ephrin-B2 and its phosphorylation in the tumour cells has been previously linked to GBM invasiveness, albeit not in the context of GSC." (PMID 27350048, 2016). "Thus, Ephrin-B2 drives tumour initiation by mediating vascular association and proliferation of human GSC." (PMID 27350048, 2016). "Notably, due to the cross-reactive nature of antibody with murine ephrin-B2, mAb EC8 also identified tumor-associated vasculature, simultaneously detecting ephrin-B2 in human tumor as well as ephrin-B2 in murine host." (PMID 22292016, 2012). "Neovasculatures in adults sprouting from arterial vessels and capillaries, whether caused by VEGF-signaling, tissue injury, or tumor growth, were found to express ephrin-B2." (PMID 22292016, 2012). "In conclusion, EphB4-ephrin-B2 pathway is induced early in PC and appears to contribute to tumor initiation and progression." (PMID 40044981, 2025). "Rapid, deep and sustained regression of established tumors supports the sustained contribution of EphB4-ephrin-B2 in tumor progression." (PMID 40044981, 2025). "Clinically, ephrin-B2 expression correlates with high tumor grade and lower Karnofsky performance scores, serving as an independent prognostic marker for shorter progression-free survival." (PMID 41200151, 2025).
tumor (continued). "The researchers developed an EPHB4-CAR-T cell (product name AP8901) that can specifically recognize and kill malignant tumor cells expressing the EPHB4 receptor by modifying ephrin B2, the natural ligand of the EPHB4 receptor." (PMID 40842575, 2025). "Upregulation of ephrin-B2 enhances tumor initiation, while its inhibition, genetic or antibody-mediated, significantly impairs tumor progression in preclinical models." (PMID 41200151, 2025). "In breast cancer, for instance, EphB4–ephrin-B2 forward signaling exerts tumor-suppressive effects, whereas ligand-independent EphB4 activity can promote tumor growth and invasion depending on the cellular context." (PMID 41009819, 2025). "The intravenous injection of ephrin-B2-modified EVs into an ID8 ovarian tumor-bearing mouse model resulted in significantly enhanced tumor-specific accumulation." (PMID 40284522, 2025). "Secondly, EphB4-ephrin-B2 pathway continue to promote tumor progression even in androgen deprivation and thus hormone refractory tumor." (PMID 40044981, 2025). "Our phopho-western blot data support that activating EphB4 while simultaneously avoiding activation of EFNB2 using various therapeutic strategies such as the EFNB2-Fc-His plasmid provides maximal benefit to reducing local tumor growth and distant metastases." (PMID 39091728, 2024). "ITGA5 stimulated tumor progression via up regulating EFNB2 in laryngeal squamous cell carcinoma (LSCC)." (PMID 38741195, 2024). "Interest in this combination is driven by the high expression of Ephrin-B4 in urothelial carcinoma and its driving role in tumor angiogenesis through the activation of its target protein, Ephrin-B2." (PMID 38540132, 2024). "EFNB2-promoted tumor growth in the LM and liver injection models was significantly reduced after the inhibition of EPHB4 by siRNA and NVP-BHG712." (PMID 36376513, 2023). "After being activated by its ligand ephrin-B2, the EphB4 receptor was shown to have tumour-suppressing effects in mice xenografts of breast cancer." (PMID 36830852, 2023). "SW480 cells transfected with EFNB2 full length (EFNB2 FL) exhibited more severe metastatic tumor burden than transfected with empty vector." (PMID 36376513, 2023). "To confirm the effect of EFNB2 on CRC LM, we injected sh-NC or sh-EFNB2 SW620 cells into the spleen of nude mice to establish the LM model and found that EFNB2 knockdown reduced the tumor burden of CRC LM." (PMID 36376513, 2023). "Then, we injected sh-EFNB2 or sh-NC SW620 cells into the liver of nude mice, and found that EFNB2 knockdown significantly inhibited the growth of CRC tumor tissue in the liver." (PMID 36376513, 2023). "Initial studies reported that soluble EPHB4 blockers, inhibiting the ephrin-B2 forward signaling in venous endothelial cells and the backward signaling in the arterial endothelium, diminish tumor growth." (PMID 36769332, 2023). "IHC staining also showed that tumor sections from nude mice that had been injected subcutaneously with ITGA5 KO2 LIU-LSC-1 cells expressed less EFNB2 protein, while ITGA5 OE TU177 cells showed a higher expression level of EFNB2." (PMID 36438491, 2022). "In HCC, the expression levels of EFNA1, EFNA3, EFNA4, EFNB1, and EFNB2 were significantly higher in tumor tissues than in normal tissues." (PMID 36052169, 2022). "The expression of EFNA1, EFNA3, EFNA4, EFNB1, and EFNB2 was significantly increased in tumor tissues compared with normal tissues." (PMID 36052169, 2022). "Consistent with the results in vitro, EFNB2 knockdown markedly retarded tumor progression, whereas EFNB2 overexpression rigorously promoted tumor growth." (PMID 36438491, 2022). "Endothelial cell rich tumor compartments, specifically, hyperplastic blood vessels and microvascular proliferative areas show increased EFNB2 and EPHB4 expression." (PMID 35629359, 2022). "Our study not only highlights the tumor supportive role of EFNB2 in LSCC but also demonstrates that EFNB2 is a substantial effector of the mTORC1-ITGA5 pathway." (PMID 36438491, 2022).
tumor (continued). "We found that the expression of EFNA1, EFNA2, EFNA3, EFNA4, EFNB1, and EFNB2 was upregulated in the tumor tissues of most cancers compared with corresponding normal tissues." (PMID 36052169, 2022). "Intravital imaging identified ephrin-B2 on endothelial cells and GSCs as an important regulator of vessel co-option and B11, a single-chain variable fragment directed against ephrin-B2 efficiently blocked cooption and tumor growth." (PMID 35433447, 2022). "In this study, we developed a novel angiogenesis score and feature genes (MMRN2, CLEC14A, ACVRL1, EFNB2, and TEK) which was associated with tumor angiogenesis microenvironment and prognosis in KIRC patients." (PMID 33761933, 2021). "The number and size of tumor vessels were significantly increased under the Ephrin-B2-Fc application, indicating a potential pro-angiogenic effect in the therapeutic setting." (PMID 34360793, 2021). "Under these conditions, Ephrin-B2-Fc leads to a reduction of metastatic loci and a prolonged time window until neurological deficits occur if applied during the dissemination of tumor cells." (PMID 34360793, 2021). "In the context of cancer therapy, blocking the mobilization of hematopoietic stem/ progenitor cell by inhibiting EphB4-ephrin-B2 communication also resulted in reduced infiltration of the hematopoietic stem/progenitor cells into murine tumor models." (PMID 33634116, 2021). "Ephrin-B2 expression, contrary to the seemingly tumor suppressive properties of ephrin-A5, was found elevated in CRC samples, with frequent enhancement on the luminal surface of carcinoma epithelium." (PMID 34445116, 2021). "In this preventative therapy, the effects on tumor–endothelial cell interactions under ligand-dependent conditions, i.e., in efnb2lox/lox control animals with physiological endothelial Ephrin-B2 expression were investigated." (PMID 34360793, 2021). "Six overexpressed and mutated tumor antigens associated with poor prognosis and infiltration of antigen presenting cells were identified in PAAD, including ADAM9, EFNB2, MET, TMOD3, TPX2, and WNT7A." (PMID 33648511, 2021). "In metastatic disease, both proteins are associated with organ-specific metastasis development, depending on the expression of both Ephrin-B2 and EphB4 on tumor- and organ-specific endothelial cells." (PMID 34360793, 2021). "This molecule, termed bi-directional ephrin agonist peptide (BIDEN-AP), can inhibit ephrin-B2 endothelial cell angiogenic signaling, while also activating EphB4 dependent tumor-suppressive signaling in tumor cells." (PMID 33634116, 2021). "Ephrin-B2-Fc induces a comparable effect by increasing spinal metastasis when applied during the dissemination of circulating tumor cells." (PMID 34360793, 2021). "Ephrin-B2-Fc led to a significantly decreased number of metastatic loci and significantly reduced the total metastasis volume in spinal MRI 25 days post tumor cell injection." (PMID 34360793, 2021). "Interference with this pathway using EphB4 kinase inhibition or genetic depletion of endothelial Ephrin-B2 resulted in increased dissemination of tumor cells, diverse metastatic loci in the spine, and an early onset of locomotion deficits." (PMID 34360793, 2021). "The tumor cell proliferation and angiogenesis was significantly increased under Ephrin-B2-Fc treatment." (PMID 34360793, 2021). "EphB4 would promote the tumor angiogenesis by interacting with ephrin-B2 expressed on tumor vasculature." (PMID 32316101, 2020). "Conversely, increasing evidence supports the idea that ligand-dependent EFNB2/EphB4 forward signaling is tumor suppressive." (PMID 31949258, 2020). "EFNB2 plays an important role in physiological and pathological angiogenesis, and its role in tumor vessel development has been extensively studied." (PMID 32211330, 2020).
tumor (continued). "Several groups have shown that the reverse EphB4 to EFNB2 signaling in endothelial cells plays an essential role in initiating angiogenesis and lymphangiogenesis, important processes in supporting tumor growth and metastasis." (PMID 31949258, 2020). "For example, EFNB2-Fc–mediated EphB4 phosphorylation activated Abl family tyrosine kinase and Crk adaptor protein in tumor cells, which led to significant tumor-suppressive activity." (PMID 31949258, 2020). "In summary, our studies provide comprehensive evidence to support the use of BIDEN-AP for targeting bi-directional EphB4/EFNB2 signaling to reduce tumor growth and metastasis and to overcome resistance to antiangiogenic therapy." (PMID 31949258, 2020). "Patients that had tumours with high expression of EFNB2 had low clinical response to neoadjuvant therapy." (PMID 31781477, 2019). "Our data demonstrated that combining EphB4-ephrin-B2 inhibitor with RT was equally effective to that of anti-PDL1+RT in terms of anti-tumor growth response." (PMID 30400822, 2018). "The first strongly suppressed tumor growth of highly expressing ephrin-B2 GSCs orthotopically implanted in mice, the latter induced a dose-dependent tumor regression of U251MG and BAH1 cells subcutaneously xenografted mice." (PMID 29849945, 2018). "Our study provides the first insight into a novel role for EphB4-ephrin-B2 interaction in modulating tumor immune microenvironment in HNSCC." (PMID 30400822, 2018). "We observed that inhibition of EphB4-ephrin-B2 signaling in vivo significantly reduced tumor growth and decreased the infiltration of Tregs, TAMs, and increased infiltration and activation of Teffector cells, without affecting CD4 T cell numbers." (PMID 30400822, 2018). "The end point is increased expression of ephrin B2 and enhanced de novo tumor arteriogenesis for tumor progression." (PMID 28186980, 2017). "As one of the key genes in angiogenesis, ephrin-B2 is very important in regulating embryonic and adult angiogenesis and tumor angiogenesis." (PMID 28489586, 2017). "Considering its positive roles in promoting endothelial cell proliferation and migration, ephrin-B2 is expected to be a therapeutic candidate in angiogenesis-related diseases and tumor." (PMID 28489586, 2017). "SCID mice with implanted SAS-L1 cells in the tongue exhibited tumor cell engraftment to the tongue and metastasis to cervical lymph nodes, whereas injection of EFNB2 siRNA into the tongue significantly reduced the number of metastatic cervical lymph nodes." (PMID 29190834, 2017). "The findings from the current study indicate that ephrin-B2 targeted therapy acts not only on vascular and lymphatic endothelial cells but also directly on cancer cells, thereby additively suppressing tumor progression." (PMID 29190834, 2017). "Tumor associated endothelial cells (TAECs) exposed to LPA demonstrated sustained nuclear PKD-1 phosphorylation, and elevated mRNA levels of ephrin B2, and reduced mRNA expression of CD36." (PMID 28186980, 2017). "We found that injection of EFNB2 siRNA suppressed tumor growth significantly, which suggested that ephrin-B2 in OSCC cells promoted tumor growth in vivo." (PMID 29190834, 2017). "In tumors, ephrin-B2 is widely expressed in blood vessels and involved in tumor angiogenesis as well as neovascularization via promotion of vascular endothelial precursor cell adhesion to the tumor site." (PMID 29190834, 2017). "Overall, these results suggested that ephrin-B2 level was higher in OSCC cells than in human keratinocytes and that ephrin-B2 level was correlated with the malignant potential of tumor cells." (PMID 29190834, 2017). "In contrast, soluble ephrin-B2-Fc molecule suppresses growth of head and neck squamous cell carcinoma xenografts by inducing maturation/stabilization of vessels in the tumor." (PMID 28194092, 2017).